PTX3 (pentraxin 3)
Diseases named in the same sentence as PTX3 in open-access papers (continued):
Sharing a sentence is not in itself a finding about the gene and the disease.
shigellosis (3 papers, 2018 to 2025). Shigellosis is a bacterial infection leading to dysentery and is caused by Shigella, which are small, ubiquitous Gram-negative bacteria belonging to the enterobacteria family. "In that particular study, we showed that levels of PTX3 in plasma from S. sonnei shigellosis patients were significantly higher than in a healthy control group and that PTX3 plasma levels in shigellosis patients were associated with symptom severity." (PMID 35956001, 2022). "We postulate that the PTX3 elevated levels at early acute phase highlight the role of PTX3 as humoral component of the innate response (“ante antibody”) in limiting the pathogenic process of shigellosis during the extracellular phase of the infection." (PMID 35956001, 2022). "We examined whether serum levels of PTX3 are positively associated with symptoms or signs of shigellosis." (PMID 35956001, 2022). "The limited number of patients for whom stool samples were collected prevented us from examining whether PTX3 levels secreted in the gut are associated with shigellosis severity as seen for PTX3 levels in blood." (PMID 35956001, 2022). "PTX3 levels were significantly higher within 2 days of disease onset than in samples collected later and were positively associated with signs or symptoms related to the severity of shigellosis such as body temperature, number of watery stools per 24 hours and bloody stools." (PMID 30532257, 2018). "We can confirm, however, that the significantly increased PTX3 levels were measured in patients with culture-proven S. sonnei shigellosis (shedding the pathogen) and suffering from typical shigellosis symptoms or signs of disease." (PMID 35956001, 2022). "We examined the interplay between levels of PTX3 and levels of anti-Shigella lipopolysaccharide (LPS) and anti-Shigella type 3 secretion system protein-IpaB antibodies in children during acute shigellosis and after recovery." (PMID 35956001, 2022). "The difference in PTX3 levels seen in stool samples between the acute patients and controls suggest that in the case of shigellosis PTX3 in stool is a more specific inflammation marker than PTX3 levels in serum." (PMID 35956001, 2022). "Here, we showed that PTX3 levels in blood are elevated during the acute phase of shigellosis compared to convalescent patients." (PMID 35956001, 2022). "Our data showed that during shigellosis PTX3 is highly secreted systemically as well as locally and the decrease in secretion during convalescence paralleled with the increase in anti-Shigella LPS and IpaB antibodies." (PMID 35956001, 2022). "PTX3 levels were significantly higher in stool samples of acute S. sonnei shigellosis patients as compared with PTX3 levels measured in stool samples of convalescent S. sonnei shigellosis patients and controls." (PMID 35956001, 2022). "We showed for the first time that PTX3 levels in stool are increased intensely during shigellosis, reaching a mean level of 16.3 ng/g stool compared with 1.1 ng/g in convalescent patients and 0.3 ng/g in healthy controls." (PMID 35956001, 2022). "There is a concerted effect of PTX3 as a humoral component of the innate response and the anti-Shigella antibody response in successfully fighting shigellosis." (PMID 35956001, 2022). "Plasma samples were collected from 31 patients in the acute stage (0–7 days after onset) of culture-proven S. sonnei shigellosis and from 19 healthy subjects and PTX3 levels were measured." (PMID 30532257, 2018). "The involvement of PTX3 in shigellosis prompted us to investigate PTX3 levels in plasma of shigellosis patients." (PMID 30532257, 2018). "Among acute cases of S. sonnei shigellosis whose maximal measured body temperature was above 39°C, the mean PTX3 level was much higher than among acute patients whose maximal measured temperature was equal or below 39°C." (PMID 30532257, 2018).
shigellosis (continued). "Due to the fact that PTX3 is secreted at the early stages of infection in response to inflammatory signals at the local site of infection (colon mucosa in the case of shigellosis), an increase over basal level can be observed within the first 6–8 h of inflammation." (PMID 35956001, 2022). "We could suggest that in natural and experimental shigellosis, epithelial cells cannot or barely produce PTX3 upon initial bacterial contact." (PMID 30532257, 2018). "It is not known how these two components of the immune response will interplay in young children in low-and middle-income countries and if local inflammation including the PTX3 response will not persist being part of the risk factors for stunting and other long-term negative effects of shigellosis." (PMID 35956001, 2022). "Finally, we suggest that the plasma level of PTX3 in shigellosis patients could act as a biomarker for infection severity." (PMID 30532257, 2018). "PTX3 serum levels correlated with specific characteristics of shigellosis severity as opposed to CRP levels, which showed no such correlation, suggesting that PTX3 might be a better indicator of the colon mucosal inflammation." (PMID 35956001, 2022). "There is a concerted effect of PTX3 as a humoral component of the innate response and the anti-Shigella antibody response, which could explain the limited mucosal invasiveness of shigellae without going deeper and turning shigellosis into a systemic disease." (PMID 35956001, 2022).
small cell lung carcinoma (3 papers, 2020 to 2025). Small cell lung cancer (SCLC) is a highly aggressive malignant neoplasm, accounting for 10-15% of lung cancer cases, characterized byrapid growth, and early metastasis. "A very promising study of pentraxin-3 on patients with small cell lung cancer found an increased expression of PTX3 in malignant tissues." (PMID 36290747, 2022).
stenosis (3 papers, 2012 to 2021). "To further elucidate the role of PTX3 in arterial stenosis, we divided PTX3 into a high and low PTX3 group according to the median PTX3 level." (PMID 31998222, 2019). "While TNF-α or IL-6-receptor inhibitors therapy was reported to reduce the production of PTX3, reflecting vascular inflammation and progression in TAK patients, IL-6-receptor antibody improved neither vascular stenosis nor thickness nor PTX-3 level." (PMID 33529185, 2021).
thrombosis (3 papers, 2017 to 2023). "In contrast, high levels of PTX3 were associated with a trend to a lower risk of thrombosis also after adjustment for JAK2V617F mutation (OR 0.57, 95% CI 0.31–1.04), suggesting a possible protective effect of PTX3." (PMID 28228104, 2017). "In a murine model of arterial thrombosis induced by FeCl3, PTX3 was only expressed by vascular cells." (PMID 37222419, 2023).
Thrombotic Microangiopathies (3 papers, 2017 to 2024). "Interestingly, we previously found that PTX3 elevation was exceptional in TTP, whereas it was elevated in typical and atypical hemolytic uremic syndrome and secondary thrombotic microangiopathies." (PMID 39337495, 2024).
thyroid cancer (3 papers, 2015 to 2025). "Future research should focus on validating these findings in larger cohorts and utilizing advanced technologies to further explore the mechanistic pathways of PTX3 in the immunologic landscape of aggressive thyroid cancer." (PMID 41373493, 2025). "Future studies incorporating these additional immune and stromal markers are warranted to further elucidate the cellular sources of PTX3 and its role within the thyroid cancer microenvironment." (PMID 41373493, 2025). "In this review, we aimed to highlight what is known, at the state of the art, regarding the connection between the long pentraxin 3 and the main thyroid diseases i.e., nodular thyroid disease, thyroid cancer and autoimmune thyroid disorders." (PMID 37025408, 2023). "In this review we will explore the role of PTX3 in the development of thyroid diseases, analyzing studies including patients with Graves’ disease (GD), thyroid nodules and thyroid cancer supported also by results obtained by our group." (PMID 37025408, 2023). "Ongoing and future researches are required to better understand these aspects and, from a clinical point of view, to determine the possible role of PTX3 as a biomarker of thyroid cancer and as a possible therapeutic target in GD." (PMID 37025408, 2023).
acute aortic dissection (2 papers, 2019 to 2025). "Peak levels of PTX3 in patients with acute aortic dissection were associated with the amount of transient pleural fluid accumulation, which may be associated with inflammatory vascular permeability." (PMID 31703088, 2019). "Other novel inflammatory markers were also examined to determine their prognostic value in patients with Type A aortic dissection, such as S100A8/A9, pentraxin 3, chitinase 3-like 1, and S100B." (PMID 39910669, 2025).
acute lung injury (2 papers, 2022 to 2023). A condition of lung damage that is characterized by bilateral pulmonary infiltrates (pulmonary edema) rich in neutrophils, and in the absence of clinical heart failure. "A recent study indicated that pentraxin 3 located on the membrane of apoptotic cells facilitated macrophage efferocytosis efficiently and alleviated lung inflammation in hard metal-induced acute lung injury." (PMID 35281078, 2022).
alcoholic hepatitis (2 papers, 2019 to 2020). Acute hepatitis resulting from ingestion of alcohol. "Hepatic and plasma PTX3 was raised in alcoholic hepatitis patients and PTX3 expression was related to the disease severity and short-term mortality." (PMID 33219288, 2020). "Indeed, it has been demonstrated that PTX3 hepatic gene expression and plasma levels showed a positive correlation in patients with alcoholic hepatitis and alcoholic cirrhosis." (PMID 31061822, 2019).
anaplastic thyroid carcinoma (2 papers, 2020 to 2025). "When analyzing PTX3 levels according to AJCC stage, the difference became statistically significant (p = 0.040) when poorly differentiated and anaplastic thyroid carcinomas (PDTC and ATC) were included." (PMID 41373493, 2025).
aortic valve stenosis (2 papers, 2012 to 2025). Aortic valve stenosis (AVS) is a condition characterized by narrowing of the heart's aortic valve opening. "In conditions such as aortic valve stenosis (AS) or regurgitation (AR), PTX3 levels are significantly increased." (PMID 40244022, 2025).
bacterial meningitis (2 papers, 2023 to 2025). Inflammation of the membranes surrounding the brain and spinal cord due to a bacterial infection. "Our findings support the notion that PTX3 can serve as a biomarker to differentiate bacterial meningitis from viral illnesses, making it a valuable clinical decision tool for excluding bacterial meningitis." (PMID 39762781, 2025). "The study show that patients with bacterial meningitis presented with very high concentrations of PTX3 in the CSF on admission." (PMID 36862691, 2023). "We found, that PTX3 was significantly higher in the CSF of patients admitted with culture-confirmed bacterial meningitis compared to those with viral meningitis, viral encephalitis, neuroborreliosis, and a control group of patients without CNS infection." (PMID 36862691, 2023). "We discovered that PTX3 levels were significantly higher in the CSF of patients hospitalized with culture-confirmed bacterial meningitis compared to those admitted with aseptic meningoencephalitis, as well as to the control group of patients without CNS infection." (PMID 39762781, 2025). "The close correlation to CSF leukocytosis in especially bacterial meningitis suggests a limited prognostic value of PTX3 since CSF pleocytosis performs poorly as a prognostic factor and that primarily the absence of CSF pleocytosis is associated with poor outcomes." (PMID 36862691, 2023). "PTX3 may be used to identify patients with bacterial meningitis independently of prior treatment using PTX3 as a single biomarker." (PMID 36862691, 2023). "An increased distance to a treatment facility in rural areas is likely to increase disease severity on presentation and this could also result in higher levels of PTX3, thereby increasing the predictive values of PTX3 as a marker for bacterial meningitis in these settings." (PMID 36862691, 2023). "When comparing the diagnostic capability of CSF PTX3 and CSF leukocyte cell count the PPV and NPV for distinguishing bacterial meningitis from viral meningitis and encephalitis was similar, although CSF PTX3 performed slightly better when bacterial meningitis of unknown etiology were included." (PMID 36862691, 2023). "PTX3 cut-off values with a high PPV and NPV was equal to or better than presently used CSF biomarkers when comparing other studies, and performs better than lactate in our cohort and similar to or slightly better than CSF leukocyte cell count when diagnosing bacterial meningitis." (PMID 36862691, 2023). "Furthermore, CSF PTX3 could differentiate bacterial meningitis from other CNS infections and patients without meningitis." (PMID 36862691, 2023).
bone metabolism disorders (2 papers, 2020 to 2021). "Finally, we believe that the use of PTX3 as a marker can contribute significantly to a reduction in costs associated with diagnostic procedures and treatment of bone metabolism disorders." (PMID 33584725, 2020). "In order to gain further insights into the function of PTX3 in bone pathophysiology, we analyse the level of circulating PTX3 in two groups of patients with ageing-related bone metabolism disorders." (PMID 33931080, 2021).
bronchopulmonary dysplasia (2 papers, 2020 to 2021). Bronchopulmonary dysplasia is a chronic respiratory disease that results from complications related to lung injury during the treatment of infant acute respiratory distress syndrome in low-birth-weight premature infants or from abnormal lung development in older infants. "Additionally, the therapeutic effects of MSCs were regulated by secreted PTX-3 in a rat bronchopulmonary dysplasia model." (PMID 34572070, 2021). "Furthermore, the therapeutic effect and mechanism involving PTX3 were tested in an animal model of bronchopulmonary dysplasia, a representative inflammatory disease, and evidence for determining the minimum standards for PTX3 was acquired." (PMID 32399038, 2020).
chronic hepatitis (2 papers, 2020 to 2025). An active inflammatory process affecting the liver for more than six months. "Multivariate logistic regression on factors for HCC showed that, in comparison with chronic hepatitis, in addition to gender (OR 19.288, P = 0.003), age (OR 1.137, P < 0.001) and AFP (OR 1.001, P = 0.014), PTX3 (OR 1.639, P < 0.001) was an independent risk factor for HCC." (PMID 33219288, 2020).
chronic lung infections (2 papers, 2018 to 2024). "We aimed to evaluate the utility of PTX3 as a clinical marker in children with lower respiratory tract infections (LRTIs) and the association between PTX3 and LRTIs severity." (PMID 39294659, 2024).
chronic rhinosinusitis (2 papers, 2021 to 2024). Chronic form of sinusitis. "Studies assessing the functional state of the epithelial barrier in a group of patients with chronic rhinosinusitis showed that PTX3 was highly expressed in nasal mucosa-derived fibroblasts, contributing to the PTX3 increase." (PMID 39519095, 2024).
clear cell Renal Cell Carcinoma (2 papers, 2020). "Here, we evaluated PTX3 tissue expression and serum levels as biomarkers of clear cell renal cell carcinoma (ccRCC) and analyzed the possible role of complement system activation on tumor site." (PMID 32345771, 2020). "In the present study, we evaluated PTX3 tissue expression and serum levels as biomarkers of clear cell renal cell carcinoma (ccRCC) and analyzed the possible role of complement system activation on tumor site." (PMID 32345771, 2020). "In clear cell Renal Cell Carcinoma (ccRCC), tumor cells produce C1r and C1s and use C1q secreted by macrophages, in order to form a functional C1 complex and activate the classical pathway in IgG-containing deposits or on cell-bound pentraxin 3 (PTX3)." (PMID 33113844, 2020). "Data from the cancer genome atlas (TCGA) clear cell renal cell carcinoma patient cohort (KIRC), confirmed our findings showing a reduced survival in patients with high expression levels of PTX3." (PMID 32345771, 2020).
cleft lip (2 papers, 2021 to 2025). Congenital defect in the upper lip where the maxillary prominence fails to merge with the merged medial nasal prominences. "PTX3 gene expression is typically seen in inflammatory conditions, and as orofacial clefts have been associated with local tissue inflammation, the increased number of PTX3 gene-signal-containing cells should have been expected in the cleft lip patient group." (PMID 41226636, 2025). "Immunohistochemistry (IHC) for MSX1, RYK, NFκB p65, and CCL4 proteins and chromogenic in situ hybridization (CISH) for MSX2, RYK, and PTX3 genes were used to analyze postnatal human cleft lip tissue (15 patients) and control tissue (6 patients)." (PMID 41226636, 2025). "The information gathered in this study has provided additional insight about the presence and distribution of MSX1, RYK, NFκB p65, and CCL4 proteins and MSX2, RYK, and PTX3 genes in human cleft lip tissue." (PMID 41226636, 2025). "In cleft lip patients, most statistically significant positive correlations involved the following factors: the PTX3 gene and NFκB p65 protein, then MSX1 protein-positive cells, RYK protein-positive cells, the CCL4 protein, the RYK gene, and then MSX2 gene-signal-containing cells." (PMID 41226636, 2025). "This indicates that, although the presence of inflammation in the cleft lip patient group was not present, which would affect and increase the number of PTX3 gene-containing cells to significant levels, this factor still significantly correlated with the RYK and NFκB p65 proteins." (PMID 41226636, 2025). "In fact, the roles of PTX3 and PF4 in cleft lip and palate have never been reported before and we suggest this as a potential new avenue for investigation since they modulate the binding of bFGF with its receptors." (PMID 34068496, 2021).
cognitive decline (2 papers, 2019 to 2024). "A previous study found plasma PTX3 to be associated with cognitive decline in older women, but not men, suggesting that the association between this protein and brain function may occur through a sex-specific process." (PMID 39482741, 2024).
coronary stenosis (2 papers, 2019 to 2025). Narrowing of the coronary artery lumen diameter. "This proof-of-concept study aimed to explore the association between galectin-3, pentraxin-3, systemic inflammatory markers, the severity of coronary stenosis, and AF burden in a cohort of patients with CCS and/or AF." (PMID 40430046, 2025). "Our data support this distinction: galectin-3 was more prominently associated with the severity of coronary stenosis, whereas pentraxin-3 showed variable expression across AF subtypes, potentially reflecting dynamic endothelial or inflammatory activation rather than a fixed fibrotic state." (PMID 40430046, 2025). "Seven out of nine cases of the coronary stenosis group and 4 out of 5 cases of the myocardial rupture group in the ACS groups exhibited a plasma PTX3 concentration less than 110.0 ng/mL, which is the 97.5th percentile in the control group." (PMID 31147578, 2019). "Conversely, all but one of the cases in the coronary stenosis group without coronary thrombi had a plasma PTX3 concentration not significantly different from the control group." (PMID 31147578, 2019).
cutaneous leishmaniasis (2 papers, 2025 to 2026). Leishmaniasis affecting the skin. "Collectively, our findings identify PTX3 as a key regulator of secondary immunity in cutaneous leishmaniasis and underscores the importance of IL-17 in this process." (PMID 41743710, 2026). "In cutaneous leishmaniasis, PTX3 expression is increased in skin lesions and correlates with disease severity." (PMID 41471254, 2025).